NACA4P (NACA family member 4, pseudogene)
Synonyms: NACAP1; FKSG17
Gene: Transcribed processed pseudogene on chromosome 8 (101,368,910 to 101,369,550, forward strand). Ensembl gene ENSG00000228224.
Diseases named in the same sentence as NACA4P in open-access papers:
NACA4P is named in the same sentence as 7 diseases in open-access papers, as found by Europe PMC text mining. Sharing a sentence is not in itself a finding about the gene and the disease.
NACA4P shares sentences with these, for which no sentence is quoted: arterial hypertension (1 paper); cancer (1); COVID-19 (1); fetal growth restriction (1); infection (1); lung carcinoma (1); prostate carcinoma (1).